BMAL1 (basic helix-loop-helix ARNT like 1)
Diseases named in the same sentence as BMAL1 in open-access papers (continued):
Sharing a sentence is not in itself a finding about the gene and the disease.
tumor (continued). "In humans, lower BMAL1 expression was associated with poorer survival rate, and correlated with higher tumor stage, poorer histological differentiation, and increased vascular invasion in PDAC." (PMID 31379749, 2019). "Considering the importance of the Bmal1 gene in cancer prevention and its association with the clock system, we investigated the expression of tumor suppressor genes to determine if Bmal-/-differentially express these genes." (PMID 31523185, 2019). "Inactivation of Per2 caused deregulation of Bmal1 expression which contributed to a high incidence of tumor formation." (PMID 27492458, 2016). "In addition, disrupted or mutated Bmal1 contributes in all stages of cancer including tumorigenesis, protein synthesis, tumor progression, as well as metastasis." (PMID 40495887, 2025). "Furthermore, we suggest that remodeling p62’s ability to accumulate in the nucleus can inhibit BMAL1-associated tumor proliferation." (PMID 40638681, 2025). "Deficiency in BMAL1 has been associated with reduced inflammatory responses and altered metabolic processes in microglial cells, suggesting its role in modulating immune cell activity within the tumor microenvironment." (PMID 40191195, 2025). "Loss of Bmal1 perturbed the homeostasis of stem cell population and increased tumor initiation." (PMID 37845346, 2023). "Moreover, alterations in Bmal1 play a critical role in the regulation of cell proliferation in cancers, which are linked to an acceleration in tumor development and modifications in responses to anti-cancer drugs." (PMID 37834478, 2023). "g., uncovering the mechanism through which Bmal1 knockout causes accelerated tumor growth could lead to therapeutic vulnerabilities)." (PMID 37262074, 2023). "It promotes the survival of tumor cells, which may be associated with the inhibition of BMAL1 expression by miR-211 induced by PERK87,216–218." (PMID 36647780, 2023). "We observed a loss of Apc copy number in Apc+/− and Apc+/−;Bmal1−/− tumor organoids versus WT." (PMID 35947664, 2022). "We hypothesized that Bmal1 disruption may drive transformation and tumor spheroid formation by increasing the mutation rate at the Apc locus and even genome-wide." (PMID 35947664, 2022). "Additionally, circadian clock modification due to BMAL1 mutations accelerates tumor growth or the whole carcinogenesis process." (PMID 36556190, 2022). "Notably, SR1078 anti-tumor activity was associated with the restoration of BMAL1 protein levels in the xenograft tumors." (PMID 34183658, 2021). "Another team also found that knocking out two genes, Bmal1 and Per2, caused tumours to grow faster." (PMID 31744421, 2019). "Bmal1 and Per2 have been demonstrated to have tumor suppressor activities and alteration of their promoter methylation has been linked with poor clinical outcome and tumor progression in hematological malignancies and gliomas." (PMID 31040792, 2019). "Overall, the amplification of apoptosis by BMAL1 knockout mutation in MCF10A could suggest that BMAL1 deletion might have an anti-tumor effect in certain types of cells." (PMID 30375470, 2018). "Moreover, another core circadian gene BMAL1 was also found to be associated with the NPAS2-mediated tumor cell survival in HCC." (PMID 28333141, 2017). "Moreover, circadian clock alteration due to mutations of single clock genes, such as Per2 or Bmal1, accelerates tumor growth or the whole carcinogenesis process." (PMID 28196531, 2017). "As shown, a high tumor TSA level is also associated with low nuclear BMAL1 levels." (PMID 19688113, 2009). "Additionally, we propose that modulating p62’s ability to accumulate in the nucleus could serve as a strategy to inhibit BMAL1-associated tumor proliferation." (PMID 40638681, 2025).
tumor (continued). "In addition to the stimulation of tumor fibrosis, deficiency of Bmal1 and its downstream circadian genes in mice increases fibrotic components in other tissues and organs, including lung, liver, and kidney, which may accommodate metastatic cancer cells." (PMID 37330661, 2023). "However, BMAL1 expression level was negatively associated with tumor size and distant metastasis." (PMID 36439870, 2022). "Quite interestingly, recent reports demonstrated that in mammary gland, selenium administration induces upregulation of another circadian protein, PER2, in a BMAL1-independent manner and that this upregulation may underlie tumor preventive properties of selenium compounds." (PMID 22249125, 2011). "In DGCs, copper or ES treatment similarly reduced BMAL1 levels, suggesting that exogenous excess copper induces BMAL1 degradation in tumor cells." (PMID 41480765, 2026). "Genes such as BMAL1 and PER cause a reduction in the expression of c-Myc while the tumor is progressing and developing." (PMID 39812541, 2025). "For instance, key CRGs such as CLOCK and BMAL1 have been shown to modulate the functional state of immune cells within the tumor microenvironment, thereby affecting the efficacy of immunotherapy." (PMID 40191195, 2025). "QPCR and Western blot data indicated that BMAL1 mRNA and BMAL1 protein expression were higher in hypoxic tumor cells than in normoxic cells after L-OHP treatment (p < 0.05)." (PMID 40535800, 2025). "In this study, our results suggest that the HIF-1α/BMAL1/ALDOC pathway functions to enhance anaerobic glycolysis in tumor cells, thus reducing the sensitivity of CRC to L-OHP." (PMID 40535800, 2025). "This study not only identifies a novel melatonin-driven signaling pathway dependent on the core circadian gene BMAL1 but, more importantly, integrates circadian regulation, metabolic reprogramming, and tumor suppression into a coherent framework." (PMID 41228459, 2025). "Here, we demonstrate that BMAL1 forms a transcriptionally active heterodimer with HIF2α in ccRCC-derived cells and contributes to HIF2α-driven gene expression, cell and tumor growth." (PMID 40595592, 2025). "Disruptions in circadian clock genes like CLOCK and BMAL1 can lead to immune dysregulation, creating an environment conducive to tumor progression." (PMID 40191195, 2025). "Consistently, we found that overexpression of nuclear-localized p62 enhanced the degradation of endogenous BMAL1 and suppressed tumor cell growth." (PMID 40638681, 2025). "When BMAL1 function is compromised, as seen in various LC studies, cells bypass these checkpoints, leading to unregulated cell division and tumor growth." (PMID 39812541, 2025). "Gastric-cancer spheroid assays demonstrate that nightly (but not daytime) melatonin pulses synchronise T-cell NAD+ oscillations, sharpen granzyme-B release and restrain tumour growth—an effect abrogated in BMAL1-knockout mice." (PMID 40791587, 2025). "Overexpression of BMAL1 robustly increased the growth of xenograft tumors, while overexpression of BMAL1 D144A increased tumor growth to a much lesser extent." (PMID 40595592, 2025). "The association between circadian rhythm disruption and cancer development is of increasing interest, and the core biological clock gene BMAL1 plays a key role in tumor suppression." (PMID 41228459, 2025). "For instance, in lung cancer, dysregulation of circadian genes like BMAL1 and PER2 has been associated with tumour growth and metastasis." (PMID 40382284, 2025). "This work involved using real-time luciferase reporters of Per2 and Bmal1 to characterize the circadian clock in various tumor cell lines." (PMID 40133704, 2025). "They observed that Bmal1 downregulation can induce tumour development, which can further affect the response to anti-cancer drugs." (PMID 40495887, 2025). "CRGs such as CLOCK and BMAL1 play pivotal roles in modulating the tumor immune microenvironment, influencing immune cell function and potentially contributing to immune evasion mechanisms." (PMID 40191195, 2025).
tumor (continued). "The core clock genes Clock and Bmal1 directly regulate the expression of the interleukin‐20 receptor subunit beta (IL‐20Rβ), thereby enhancing the responsiveness of tumor cells to IL‐20 and activating the critical JAK/STAT prosurvival pathway." (PMID 41143275, 2025). "The circadian clock regulates the osteogenic potential by inhibiting BMAL1 expression, and the impaired expression of BMAL1 and PER1–2 causes tumor growth in mouse embryonic tissue." (PMID 41234239, 2025). "Knockdown of Bmal1 in B16 tumors averted the actions of dexamethasone on cell cycle events and tumor growth." (PMID 40495887, 2025). "After treatment with siHIF-1α, L-OHP-treated hypoxic tumor cells exhibited lower BMAL1 mRNA and protein expression levels than the control group (NC)." (PMID 40535800, 2025). "On day 28, the mice that were injected with BMAL1-depleted cells showed a significantly smaller tumor volume of 92.2 ± 17.9 mm^3, in contrast to the control group, which exhibited a larger tumor volume of 544.9 ± 34.6 mm^3." (PMID 38703241, 2024). "Here, we demonstrate that BMAL1 forms a transcriptionally active heterodimer with HIF2α in ccRCC-derived cells and contributes to HIF2α-driven gene expression, cell and tumor growth, and sensitivity to growth suppression by the HIF2α antagonist PT2399." (PMID 39070610, 2024). "Specifically, the control group exhibited an average tumor weight of 0.53 ± 0.05 g, whereas tumors that derived from mice with BMAL1-depleted cells weighed only 0.10 ± 0.01 g." (PMID 38703241, 2024). "Within the cohorts receiving venetoclax treatment, the administration of this therapeutic agent resulted in a substantial reduction in tumor size among mice harboring BMAL1 knockdown cells." (PMID 38703241, 2024). "M2 subtype promotes tumor proliferation and metastasis by reducing BMAL1 expression in TAM and regulating tumor-related protein expression and cell apoptosis." (PMID 38678017, 2024). "The autophagy‐mediated degradation of BMAL1 favors lipid peroxidation and cell death in human tumor cell lines." (PMID 38385622, 2024). "Seemingly contradictory findings were reported for BMAL1, which was shown to act both as an oncogene, as well as a tumour suppressor." (PMID 38378853, 2024). "Dexamethasone’s effects on tumor growth and cell cycle events were inhibited in B16 tumors by knocking down the key clock gene BMAL1." (PMID 38892035, 2024). "By the 21st day, the mice that were injected with BMAL1-depleted cells demonstrated a tumor volume measuring 207.0 ± 39.8 mm^3, whereas the control group exhibited a larger tumor volume of 587.9 ± 35.8 mm^3." (PMID 38703241, 2024). "Circadian rhythm genes, such as BMAL1, can control endothelial cell cycle and thereby affect angiogenesis in development process and tumor progression." (PMID 38607733, 2024). "As a transcription factor, BMAL1 not only impacts the occurrence, progression, and metastasis of tumors, but also correlates with the sensitivity of tumor cells to chemotherapeutic drugs." (PMID 38703241, 2024). "Our study has revealed that reducing BMAL1 expression increases the responsiveness of AML cells to the anti-tumor medications venetoclax, dasatinib, and sorafenib." (PMID 38703241, 2024). "Concerning the weight of the tumors, there was a notable decrease in tumor weight in the BMAL1 knockdown group." (PMID 38703241, 2024). "In the sorafenib treatment groups, the administration of sorafenib effectively resulted in a significant reduction in tumor size in mice that carried BMAL1 knockdown cells compared to the control group." (PMID 38703241, 2024). "To provide insight into Bmal1’s effects on B16-F10 tumor growth, we used QuantSeq 3′ mRNA sequencing to identify differentially expressed genes (DEGs) between control (Ctrl) and Bmal1-null in B16-F10." (PMID 38245503, 2024). "In the dasatinib treatment groups, the administration of dasatinib led to a considerable decrease in tumor size in mice carrying BMAL1 knockdown cells." (PMID 38703241, 2024).
tumor (continued). "Many tumors exhibit disruption of circadian rhythms 1, and deletion of the clock component BMAL1 exacerbates tumor burden in several genetically engineered mouse models of cancer 2,3." (PMID 39070610, 2024). "Specifically, on day 37, the group of mice injected with BMAL1-depleted cells displayed a tumor volume of 119.4 ± 15.8 mm^3, while the control group exhibited a much larger tumor volume of 560.5 ± 56.7 mm^3." (PMID 38703241, 2024). "The balance between BMAL1 and HIF1α affects macrophage metabolism and anti-tumor immunity, and BMAL1 knockout increases septic mice mortality." (PMID 38678017, 2024). "Co-injection of cancer cells and Bmal1 KO macrophages promotes tumor growth with reduced CD8+ T cell infiltration." (PMID 38678017, 2024). "The outcomes of our study demonstrated that mice receiving stable BMAL1-depleted cells exhibited significantly reduced tumor sizes." (PMID 38703241, 2024). "The studies published so far showed both oncogenic and tumour suppressor functions of BMAL1, CLOCK, PER1, PER2, PER3, CRY2, and REV-ERBβ." (PMID 38378853, 2024). "The tumor weight in the group of mice with BMAL1 knockdown was measured to be 0.28 ± 0.06 g, whereas the control group exhibited a notably higher tumor weight of 0.76 ± 0.12 g." (PMID 38703241, 2024). "The tumor suppressiveeffect was maintained in xenograft models, resulting in a smallertumor size and reduction in invasiveness when BMAL1 was overexpressed." (PMID 39072055, 2024). "In concurrence with our in vitro experimental results, the depletion of BMAL1 exhibited a pronounced deceleration in tumor growth, characterized by notable reductions in tumor volume and weight." (PMID 38703241, 2024). "The therapeutic response indicated a significant decrease in tumor volume and weight among the group of mice with BMAL1 knockdown compared to the control group." (PMID 38703241, 2024). "Research in this area is expected to advance understanding of circadian locomotor output cycles kaput (CLOCK) and brain and muscle ARNT-like protein 1 (BMAL1) in tumor diseases, and contribute to the development of new anti-tumor treatment strategies." (PMID 36647780, 2023). "We validated the clock machinery dependency in vivo with Hep3B xenografts by showing that shRNA-mediated Bmal1/Clock knockdown strongly inhibited tumor growth." (PMID 36595671, 2023). "We provide experimental evidence that excessive fibrosis is responsible for the expansion of tumor volumes in Bmal1−/− mice." (PMID 37330661, 2023). "RKO/BMAL1 cells exhibited markedly increased tumor growth in the subcutaneous xenograft model (p < 0.05)." (PMID 36806631, 2023). "Similar downregulation of active PAI‐1 was also observed in the plasma of CRC tumor‐bearing Bmal1−/− mice." (PMID 37330661, 2023). "When stratifying for tumour grade, 17 genes were found to have a significant effect survival, of which four core-clock genes (BMAL1/2, CRY2 and RORC)." (PMID 37400829, 2023). "An increase in tumor metabolite lactate was concomitant with increase in proinflammatory cytokine IL-1b and circadian factors Clock and Bmal1." (PMID 37476290, 2023). "Histological examination of lung and liver tissues further corroborated the presence of high numbers of microscopic metastases in CRC tumor‐bearing Bmal1−/− mice versus the control tumor–bearing Bmal1+/+ mice." (PMID 37330661, 2023). "Mitigation of cellular apoptosis and increases of microvessels further supported the elevated tumor growth rates in Bmal1−/− animals." (PMID 37330661, 2023). "g., Bmal1 knockout adipocytes vs wild-type adipocytes) and human datasets of tumor compared to matched (adjacent) normal tissue, where the timing of sample collection was unspecified." (PMID 37262074, 2023).
tumor (continued). "The results showed that depletion of BMAL1 significantly inhibits tumor growth in control animals injected with vehicle, as expected, and tumor growth is even more strongly suppressed in VP16-treated recipient mice carrying BMAL1-depleted xenograft tumors." (PMID 36725890, 2023). "Mechanistically, we found that inhibiting Bmal1/Clock induced dysregulation of the cell cycle regulators Wee1 and p21 which cooperatively contribute to tumor cell death." (PMID 36595671, 2023). "Immunohistochemistry analysis of metastatic nodules demonstrated marked mitigation of the FAP+, α‐SMA+, DESMIN+, PDGFRα+, and PDGFRβ+ fibrotic components in TGF‐βR1‐treated Bmal1−/− tumor‐bearing mice." (PMID 37330661, 2023). "Histological examination of lung tissues from tumor‐bearing mice corroborated the high numbers of metastatic lesions in Bmal1−/− mice." (PMID 37330661, 2023). "This demonstrated that BMAL1 and cell-autonomous circadian oscillations in both DCs and T cells are critical for the time-of-day differences in tumour volume." (PMID 36470303, 2023). "Mechanistically, Bmal1 deletion in cDCs abrogated the differences in total and antigen-specific DC numbers in the dLN after tumour engraftment, in contrast to control mice." (PMID 36470303, 2023). "The abundance of γH2AX was slightly higher in BMAL1-deficient xenograft tumors, and they increased to much higher level after VP16 treatment and increased rate of tumor cell apoptosis." (PMID 36725890, 2023). "Although plasmin activates a cascade of responses in tumors, we have found that stimulation of tumor fibrosis is the prominent process in Bmal1−/− mice." (PMID 37330661, 2023). "Together, these results demonstrate that genetic deletion of Bmal1 gene in mice leads to accelerated tumor growth rates and increased fibrotic components." (PMID 37330661, 2023). "Due to the Bmal1 has dual role in cancer therapy, there is a need to develop those selective BMAL1 agents that promote only its tumor suppressor activity." (PMID 36725890, 2023). "Immunohistochemical analysis of metastatic nodules in both lung and liver tissues from CRC and PDAC tumor‐bearing mice showed that metastases in Bmal1−/− mice were enriched in stromal fibroblasts that were positive for FAP, α‐SMA, DESMIN, PDGFRα, and PDGFRβ." (PMID 37330661, 2023). "Collectively, these results indicate that BMAL1 increased tumor cell growth and metastasis in nude mice." (PMID 36806631, 2023). "It has been reported that BMAL1 can regulate metabolic reprogramming and affect the expression of PD-L1 in macrophages, suggesting that the circadian clock influences tumor development by regulating metabolic pathways." (PMID 38189049, 2023). "In vehicle‐treated control CRC tumor–bearing mice, high numbers of metastatic nodules were detected in Bmal1−/− mice." (PMID 37330661, 2023). "Together, these data are consistent with the finding that TGF‐β is responsible for tumor fibrosis and accelerated tumor growth in Bmal1−/− mice." (PMID 37330661, 2023). "Using our KPC and KPC-BKO cells, we found accelerated tumor growth in our syngeneic in vivo model with Bmal1 functional knockout." (PMID 37262074, 2023). "A large body of evidence has indicated that the CRG (CLOCK, BMAL1, PER, CRY, etc.)is associated with tumor progression, prognosis, and treatment response." (PMID 36895015, 2023). "Histological examination of CRC tumors discovered high contents of Masson's trichrome positive fibrotic components in tumor tissues grown in Bmal1−/− mice relative to Bmal1+/+ animals." (PMID 37330661, 2023). "Approximately 83% of CRC tumor‐bearing Bmal1−/− mice showed visible surface metastatic nodules, and only 33% of the control tumor–bearing Bmal1+/+ mice had visible metastases." (PMID 37330661, 2023). "qRT-PCR and Western blotting assays demonstrated that both mRNA and protein expression levels of BMAL1 were lower in tumor tissues than in paired neighboring healthy tissues." (PMID 36439870, 2022).